ZNF384 (zinc finger protein 384)
Diseases named in the same sentence as ZNF384 in open-access papers (continued):
Sharing a sentence is not in itself a finding about the gene and the disease.
asthma (1 paper, 2017). "Three CpG sites were significantly associated (FDR < 0.05) with asthma at age 4: cg22971191 in SLC10A2 (solute carrier family 10 (sodium/bile acid cotransporter) member 2), cg18515031 in C10orf104 (chromosome 10 open reading frame 104) and cg05712073 in ZNF384 (Zinc Finger Protein 384)." (PMID 28056824, 2017).
colitis (1 paper, 2023). Inflammation of the colon. "In colon samples of chronic or acute colitis mice models, only Cebpa expression was altered by L. intestinalis, whereas Znf384 was unchanged." (PMID 37983567, 2023).
colon cancer (1 paper, 2025). "Our findings suggest that ZNF384 plays a more central role in colon cancer progression than previously recognized, potentially serving as a crucial hub in the regulatory network that governs tumor development." (PMID 40405535, 2025). "A strength of our approach lies in its depth of network analysis, which has revealed ZNF384 as a previously unrecognized master regulator in colon cancer progression." (PMID 40405535, 2025). "Notably, our study is the first to establish the intricate interplay between ZNF384 and key microRNAs in the context of colon cancer, offering novel insights into tumor regulation mechanisms." (PMID 40405535, 2025). "Especially, with which mRNA(s) and/or miRNA(s) ZNF384 interacts and how these interactions function via DNA damage and related protein within the context of colon cancer remain unclear." (PMID 40405535, 2025).
head and neck cancer (1 paper, 2015). A primary or metastatic malignant neoplasm affecting the head and neck. "As a proof of principle, integrated analysis of copy number variation, exome and transcriptome of 4 head and neck cancer cell lines and TCGA HNSCC dataset identify NRBP1, UBR5, ZNF384 and TERT as novel candidate oncogenes in HNSCC." (PMID 26572163, 2015).
Insulin resistance (1 paper, 2025). Increased resistance towards insulin, that is, diminished effectiveness of insulin in reducing blood glucose levels. "The findings suggest that ZNF384, as a transcription factor, mediated the regulation of MVL on insulin resistance by controlling the expression of Ggpps." (PMID 40412522, 2025). "We found that the over-colonization of R. torques led to increased MVL content in the organism, triggering the increase in nuclear localization of ZNF384 and subsequently increasing the expression of GGPPS, thereby impacting insulin resistance, contributing to the classification of MUO and MHO." (PMID 40412522, 2025).
metabolic syndrome (1 paper, 2022). A cluster of metabolic risk factors for CARDIOVASCULAR DISEASES and TYPE 2 DIABETES MELLITUS. "ZNF384 is the potential transcription factor that may modulate STFs PPARG, ZNF415, HLX, and ANHX, thus subsequently triggering hyperinflammatory states and metabolic syndromes." (PMID 35669784, 2022).
mucinous tumors (1 paper, 2012). "These include: FH, GMPS, PIK3CA, EIF4A2, ZNF384, and SS18L1 (amplifications in serous tumors); TET2, FGFR10P, NF1, ERBB2, and SH3GL1 (deletions in serous tumors) and ERBB2 (amplifications in mucinous tumors)." (PMID 23078675, 2012).
myeloma (1 paper, 2021). "Similarly, myeloma cells appear to be addicted to CBFB and ZNF384 which have not been linked to myeloma PC biology thus far." (PMID 34521827, 2021).
plaque psoriasis (1 paper, 2022). "Targeting ZNF384 is a potential therapeutic method for treating plaque psoriasis and AD." (PMID 35669784, 2022).
serous ovarian cancer (1 paper, 2025). "Another study on serous ovarian cancer (SOC) discovered that ZNF384 stimulated the growth of SOC in mice and enhanced the metastatic properties of tumor cells." (PMID 40717692, 2025).
viral infection (1 paper, 2024). "For instance, the transcription factor Zfp384 (zinc finger protein 384), limiting cytokine/chemokine gene transcription in macrophages in response to viral infection, or Zbtb2 (zinc finger and BTB domain containing 2) inhibiting NF-κB activation were upregulated in KSRP-deficient BMDM." (PMID 38612694, 2024).
cancer (19 papers, 2017 to 2025). A tumor composed of atypical neoplastic, often pleomorphic cells that invade other tissues. "To precisely identify central genes associated with both cancer and ZNF384, we employed the WGCNA algorithm to construct a gene co‐expression network." (PMID 40405535, 2025). "Subsequently, by overlapping the genes in the red module with DEGs, we identified a subset of 84 genes that are related to cancer and associated with ZNF384." (PMID 40405535, 2025). "These genes are potentially crucial in understanding BP and pathways underlying the association between cancer and ZNF384." (PMID 40405535, 2025). "Also the zinc finger genes Znf384, which are associated with cancer EMT and metastasis and Zeb1 transactivation were highlighted." (PMID 41446274, 2025). "ZNF384 is shown to upregulate the expression of Cyclin D1 to promote the proliferation of cancer cells." (PMID 40405535, 2025). "Studies have explored a possible cancer-promoting activity of the transcription factor ZNF384 in different cancers." (PMID 38049415, 2023). "In our experimental findings, force expression of ZNF384 was related to malignancy, whereas depletion of ZNF384 suppressed the colonization capacity of cancer cells." (PMID 36100877, 2022). "To unveil the role of ZNF384 in cancer progression, we sought to identify the function of this transcription factor and its underlined mechanism." (PMID 36100877, 2022). "Although the precise mechanisms remain to be clarified, these results suggest that targeting ZNF384 or its downstream effectors could serve as a novel therapeutic approach for cancer." (PMID 40405535, 2025). "Unlike previous studies that focused on isolated molecular interactions, our comprehensive network‐based methodology has illuminated a complex web of regulatory relationships, providing the first systematic characterization of ZNF384's role in cancer regulatory networks." (PMID 40405535, 2025). "Collectively, our results explored the critical oncogenic function of ZNF384 and its regulation by the feedback loop, which can be a potential therapeutic target to inhibit the proliferation and metastasis of cancer cells, as well as re-sensitize them to chemotherapy." (PMID 36100877, 2022). "Studies have proposed that ZNF384 could be a potential oncogene and it is overexpressed in various human cancers 49, 60-62." (PMID 33754016, 2021). "Although various evidences indicated that ZNF384 might be a potential oncogene, which promotes the occurrence and development of cancers, the research about ZNF384 in HCC is vacant." (PMID 31168049, 2019). "To further characterize the subgroups with DUX4-IGH and ZNF384 rearrangements, we utilized previously published targeted exome sequencing data including 872 cancer genes and array-based copy number data derived from the HumanMethylation 450 k arrays from the same patients." (PMID 28806978, 2017). "Subsequent work also demonstrated the involvement of the zinc-finger protein ZNF384 in HPV-associated human cancers, although ZNF384 is not required for basal A3B expression." (PMID 28276478, 2017). "The success of our approach in revealing complex regulatory relationships, particularly those centered on ZNF384, suggests that similar strategies could be effectively applied to study other aspects of cancer biology, potentially accelerating the pace of discovery in cancer research." (PMID 40405535, 2025). "The upregulation of ZNF384 transcriptionally activates polymerase III subunit G, which in turn promotes the epithelial–mesenchymal transition in cancer cells, thereby facilitating tumor progression." (PMID 40717692, 2025). "For samples from Tokyo Children’s Cancer Study Group (TCCSG) biobank, TCF3 was the most prevalent ZNF384 fusion partner." (PMID 33816270, 2021). "However, an experimental approach is needed to verify the cooperation between H2A.Z and TFs such as SP2, ZNF384, YY1, NRF1, and NFYA in the transcriptional misregulation in cancer." (PMID 35317119, 2021).
cancer (continued). "Allo‐HSCT, allogeneic hematopoietic stem cell transplantation; CR, complete remission; KMT2Ar, KMT2A rearrangement; ND, newly diagnosed; NCCN, national comprehensive cancer network; Ph+, Philadelphia chromosome (Ph)‐positive; Ph−, Ph‐negative; RR, refractory/relapsed; ZNF384r, ZNF384 rearrangement." (PMID 40388565, 2025). "Furthermore, recent studies have demonstrated that ZNF384 might promote tumor progression through pathways beyond DDR and cell cycle, such as extracellular matrix remodeling and cancer metastasis." (PMID 40405535, 2025). "Seven genes had variants found in the cancers of at least two ‘poor’ responders but in no 'good’ responders: ATRNL1, BAIAP2L2, ZNF384, ST6GALNAC5, ENSCAFG00000030179 (human ortholog: riboflavin kinase RFK), ENSCAFG00000029320, and ENSCAFG00000007370 (human ortholog: immunoglobin IGKV4-1)." (PMID 32857815, 2020). "Nonetheless, the role and mechanism of ZNF384 in COAD have not been fully elucidated, particularly regarding its impact on cancer progression through gene regulation." (PMID 40405535, 2025).
tumor (13 papers, 2016 to 2025). "Our research study found that METTL3 mediated the m6A modification of ZNF384 in NSCLC, which in turn enhanced the expression of ZNF384 and influenced its regulatory role in tumor metastasis." (PMID 40717692, 2025). "The top ZNF384‐correlated mRNA heatmap showed the expression level of mRNA in tumor and normal samples." (PMID 40405535, 2025). "ZNF384 protein upregulation was also detected in OS tumor tissues from four representative patients (Patient #1/#3/#6/#10)." (PMID 33754016, 2021). "We also observed that high expression of ZNF384 always correlated with shorter tumor-free survival time in patients (P = 0.0016)." (PMID 31168049, 2019). "It is worth noting that the tumor tissues of over 90% of the HCC patients in our study exhibited increased ZNF384 expression." (PMID 31168049, 2019). "Toward this aim, we first identified a set of genes which are differentially expressed between tumor and normal tissues and are also related to ZNF384 using the TCGA dataset and then systematically integrated mRNAs, miRNAs, and lncRNAs into a unified ceRNA regulatory network." (PMID 40405535, 2025). "Contrary to in vitro assays, the depletion of ZNF384 in MDA-MB-231-luc cells could reduce tumor growth." (PMID 36100877, 2022). "Our results showed that ZNF384 promote tumor growth and may be a novel prognostic marker in HCC." (PMID 31168049, 2019). "These expression changes reinforce the regulatory significance of ZNF384 in COAD progression and highlight the intricate network of interactions among mRNA, lncRNA, and miRNA in tumor development." (PMID 40405535, 2025). "We found that overexpression of ZNF384 in HCC and elevated expression of ZNF384 in HCC tissues was significantly correlated with tumor recurrence (P = 0.0097)." (PMID 31168049, 2019). "Importantly, both ZNF384 and ZNF460 protein expression exhibited an increase in NPC tumor tissues (“T”), while their expression remained relatively low in adjacent normal nasopharynx epithelial tissues (“N”)." (PMID 38049415, 2023). "The ZNF384 gene harboured nsSNVs in 8 of 16 non-responding tumours (50%), but in only 2 of 15 responding tumours (13.3%)." (PMID 36248850, 2022).
brain disease (1 paper, 2022). "We then performed selective pressure analysis on the polyQ tract of the other seven brain disease-related proteins, and of two proteins not-associated with any disease (POU6F2 and ZNF384)." (PMID 34974533, 2022).
neurodevelopmental disorder (1 paper, 2025). A behavioral and cognitive disorder with onset during the developmental period that involves impaired or aberrant development of intellectual, motor, or social functions. "Recently, C2H2-ZNFs have been highlighted for their involvement in the pathological processes associated with neurodevelopmental disorders, and ZNF384 is also classified among these C2H2-ZNFs." (PMID 40033291, 2025).
ZNF384 also shares sentences with these, for which no sentence is quoted: B-cell acute lymphoblastic leukemia (6 papers); Ewing sarcoma (2); glioma (2); Alzheimer disease (1); bladder cancer (1); colon adenocarcinoma (1); dementia (1); desmoplastic small round cell tumor (1); fibrosis (1); infection (1); lymphoproliferative disorders (1); myeloid leukemia (1); retinoblastoma (1); small cell lung carcinoma (1); soft tissue tumors (1); synovial sarcoma (1); systemic lupus erythematosus (1); T-cell acute lymphoblastic leukemia (1); type 2 diabetes (1).